GLDC (glycine decarboxylase)
Diseases named in the same sentence as GLDC in open-access papers (continued):
Sharing a sentence is not in itself a finding about the gene and the disease.
diabetes (1 paper, 2021). "Additionally, our novel observation that GLDC expression is linked to glutathione production presents a possible mechanism for how altered GLDC expression might affect the progression of diabetes." (PMID 34342168, 2021). "One of the goals of this study is to determine if GLDC gene expression is elevated in diabetes and related metabolic conditions." (PMID 34342168, 2021). "The miRNA‐30d‐5p has been shown to be a negative regulator of GLDC gene expression, and to be reduced in diabetes." (PMID 34342168, 2021). "To explore the possibility that GLDC expression is a determinant of altered glycine levels in diabetes and other metabolic stress states, we measured hepatic GLDC expression in several mouse models: db/db mice, high fat diet‐induced obese mice, and normal mice after a prolonged fast." (PMID 34342168, 2021). "Given that GLDC is a key regulator of glycine levels in the body, we asked whether GLDC was in fact over‐expressed in diabetes and other metabolically stressed states, increasing glycine degradation and contributing to the observed reduction in circulating glycine levels seen in diabetes." (PMID 34342168, 2021). "Finally, the linkage between GLDC expression, glutathione production, and cellular oxidative stress suggests a potential mechanism by which altered glycine metabolism could influence the development of diabetes." (PMID 34342168, 2021).
Fabry disease (1 paper, 2025). Fabry disease (FD) is a progressive, inherited, multisystemic lysosomal storage disease characterized by specific neurological, cutaneous, renal, cardiovascular, cochleo-vestibular and cerebrovascular manifestations. "Particularly Wilson’s disease (caused by pathogenic variants in ATP7B), Fabry disease (GLA), and glycine encephalopathy 1 (GLDC) were reported to have disease onset variability and late-onset cases." (PMID 41283366, 2025).
folate deficiency (1 paper, 2026). A nutritional condition produced by a deficiency of FOLIC ACID in the diet. "Variants in the mitochondrial enzyme glycine decarboxylase (GLDC) cause a rare neurological disease, nonketotic hyperglycinemia, with expected hallmarks of brain glycine elevation and responsiveness to folate deficiency but the consequences for energy mechanisms remain unknown." (PMID 42055339, 2026).
H1N1 influenza (1 paper, 2019). "Interestingly, the genetic association of GLDC with severe H1N1 influenza was replicated in the H7N9 cohort including 102 H7N9 patients and 106 controls of healthy poultry workers." (PMID 30498026, 2019).
IgA nephropathy (1 paper, 2025). "This study reveals that glycine decarboxylase (GLDC) promotes IgA nephropathy (IgAN) progression by enhancing mesangial cell proliferation through the pyrimidine pathway." (PMID 41083822, 2025).
kidney cancer (1 paper, 2020). Primary or metastatic malignant neoplasm involving the kidney. "Therefore, UCLG1, PCK2, GLDC, have the potential to be a novel and valuable oncotarget protein for human kidney cancer." (PMID 32699530, 2020). "Kidney cancer patient with SUCLG1, GLDC, SLC12A1, PCK2, ATP1A1 and PDHA1 alteration showed highest mortality." (PMID 32699530, 2020).
Macrocephaly (1 paper, 2016). Occipitofrontal (head) circumference greater than 97th centile compared to appropriate, age matched, sex-matched normal standards. "While we observed distinct clinical features in some individuals (e.g. macrocephaly and seizures in the carriers of variants in KDM5C and GLDC, respectively), features specific to SMS are present in a sufficient number of probands." (PMID 27799067, 2016).
major depressive disorder (1 paper, 2020). An episode of depression lasting two or more weeks without an intervening episode of mania. "First, an intronic variant in GLDC was associated with increased response to citalopram and escitalopram in people with major depressive disorder." (PMID 32228266, 2020).
metastatic melanoma (1 paper, 2019). A melanoma that has spread from its primary site to another anatomic site. "Indeed, an upregulation of CD271, GLDC, and ERRFI1 in metastatic melanoma is in line with a bad prognosis." (PMID 30641895, 2019).
metastatic prostate carcinoma (1 paper, 2023). A carcinoma that arises from the prostate gland and has spread to other anatomic sites. "This evidence suggests that GLDC is highly expressed in metastatic prostate cancer and has a regulatory relationship with AR and AR-V7." (PMID 37781511, 2023).
pneumonia (1 paper, 2013). An acute, acute and chronic, or chronic inflammation focally or diffusely affecting the lung parenchyma, caused by an infection in one or both of the lungs (by bacteria, viruses, fungi, or mycoplasma.). "Active TB cases were separated from all other groups (i.e. LTBI, HC and non-TB pneumonia) based on expression of PIGC (p = 0.045), GLDC (p = 0.044) and HBD (p = 0.025)." (PMID 23375113, 2013).
renal fibrosis (1 paper, 2025). A final common manifestation of a wide variety of chronic kidney diseases characterized by glomerulosclerosis and tubulointerstitial fibrosis. "Additionally, GLDC’s regulation of glycolysis in mesangial cells was discovered, which further affects the progression of renal fibrosis and the proliferation of glomerular mesangial cells." (PMID 41083822, 2025).
tumor (50 papers, 2013 to 2026). "The results imply an important underlying mechanism of GLDC-regulated cell proliferation and tumor immune infiltration in TNBC." (PMID 36275705, 2022). "Glycine decarboxylase (GLDC) is crucial for tumour initiating cells in NSCLC, and was associated with pyrimidine metabolism to support cancer cell proliferation." (PMID 30866469, 2019). "This is evidenced by the upregulated activity of Gly metabolic enzyme Gly decarboxylase (GLDc) and an association between poor prognosis subgroups and increased GLDc staining using immunohistochemistry in these tumours." (PMID 29721167, 2018). "An underlying dependence of CR tumor cells for energy metabolism pathways such as enhanced expression of GLDC, ACC, ASNS, FDFT1, UGDH, PYCR2, etc was noted." (PMID 27470985, 2016). "Expression of stromal PSPH was associated with higher T staging (p = 0.048), whereas expression of tumor GLDC was associated with lower T staging (p = 0.008) and lower Ki-67 LI (p = 0.008)." (PMID 24979213, 2014). "For example, the elevation of glycine decarboxylase, a component of the mitochondrial glycine cleavage system, is associated with high growth rate and tumorigenic potential in tumor initiating cells." (PMID 23936142, 2013). "Glycine decarboxylase (GLDC) is overexpressed in multiple tumor types and contributes to tumorigenesis or immune evasion by unclarified mechanisms." (PMID 41728086, 2026). "Many studies have found that amino acid metabolic enzymes are closely related to biological behaviors such as tumor cell proliferation, including GLDC." (PMID 41083822, 2025). "We found that tumor volumes and weights of GLDC knock-downed ACHN cells were markedly lower than those of control ACHN cells while tumor volumes and weights of GLDC overexpressed A498 cells were markedly higher than those of control A498 cells." (PMID 39781465, 2025). "In this study, we found that knockdown of GLDC promoted the cell viability, colony formation and tumor growth." (PMID 41550650, 2025). "GLDC is a key rate-limiting enzyme in glycine metabolism and functions as an oncogene or tumor suppressor in different cancer types." (PMID 41550650, 2025). "In this work, we demonstrated that GLDC overexpression induced cell senescence and inhibited cell proliferation, migration and tumor growth in HCC." (PMID 41550650, 2025). "As expected, the expression level of GLDC was significantly decreased in tumors compared to non-tumor liver tissues." (PMID 41550650, 2025). "On the other hand, GLDC promotes mitochondrial protein lipoylation and tumor growth, indicating an oncogene role." (PMID 41550650, 2025). "We aimed to investigate the effect of GLDC on cell proliferation, migration, tumor growth and autophagy and clarified the molecular mechanism of GLDC regulating autophagy in HCC." (PMID 41550650, 2025). "In our study, we found that GLDC acted as a tumor suppressor and revealed the downstream mechanism by which induced autophagy in HCC." (PMID 41550650, 2025). "Taken together, GLDC inhibits cell proliferation, reduces tumor growth and induces cell senescence in HCC." (PMID 41550650, 2025). "GLDC acts as a driver gene, which significantly promotes tumor initiation in non-small cell lung cancer (NSCLC)." (PMID 41550650, 2025). "Recently, glycine decarboxylase (GLDC) has been recognized as a tumor‐promoting gene upregulated in various cancers." (PMID 39092293, 2024). "Lung-tumour-initiating cells had elevated levels of glycine decarboxylase, which is the enzyme responsible in the glycine cleavage pathway." (PMID 36851259, 2023). "In this context, regulation of GLDC expression has been used by malignant tumors to adapt metabolism in hypoxic conditions and is therefore relevant to tumor aggressiveness." (PMID 37781511, 2023). "GLDC is also close to rs55933544 and positively expressed in tumour cells, CD4_C4_CXCL13 cells, B cells and ECs." (PMID 36305631, 2022).
tumor (continued). "The enzymes of the mitochondrial serine/glycine metabolism are elevated in primary NSCLC tumor initiating cells, specifically, glycine decarboxylase (GLDC)." (PMID 35831624, 2022). "The GLDC-knockdown tumors were smaller than those expressing scrambled shRNA, and the addition of GSH increased the tumor size in mice with GLDC shRNA1." (PMID 35817773, 2022). "To further investigate the clinical significance of GLDC K514 acetylation, we collected 18 non-tumor (N) and 18 GBM (T) tissues from patients and performed quantitative immunoblotting analysis." (PMID 34244482, 2021). "The results indicated that GBM tissues had increased levels of GLDC, SIRT3, and pS6K (a hallmark of mTORC1 activity) and decreased levels of ACAT1, NF-X1, and GLDC K514 acetylation in comparison to non-tumor tissues." (PMID 34244482, 2021). "It has also been demonstrated that GLDC is hyperactive in different types of cancer cells and plays a fundamental role in tumor growth." (PMID 34244482, 2021). "Compared to the normal liver tissues, 278 acetylation sites in 189 proteins were down-regulated while three acetylation sites in three proteins (EP300, GRHPR, and GLDC) were up-regulated with significant differences in tumor tissues." (PMID 33093847, 2020). "GLDC expression level in tumor tissues was categorized by overall score as low (overall score 0) and high (overall score >0) expression groups." (PMID 30804330, 2019). "By contrast, in para-tumor tissue, GLDC expression level was score as 0, 1, 2, 4, and 6 in 0, 2, 10, 42, and 40 samples, respectively." (PMID 30804330, 2019). "Then, GLDC expression level in tumor tissue was scored as 0, 1, 2, 4, and 6 in 42, 15, 24, 11, and 2 samples, respectively." (PMID 30804330, 2019). "Until now, there have limited tumor studies on GLDC and the role of GLDC in tumorigenesis is under debate." (PMID 30804330, 2019). "Overexpression of mitochondrial serine hydroxymethyltransferase (SHMT2) and glycine decarboxylase (GLDC) in GBM promotes tumor growth by inhibition of PKM2 activity and reduction of oxygen consumption." (PMID 31450721, 2019). "In this sense, cysteine has been shown to be elevated in various types of cancer including LC, and the glycine decarboxylase, the enzyme responsible for glycine degradation, has been related to tumor‐initiating cells in NSCLC." (PMID 30099851, 2018). "Overexpression of GLDC in 3T3 mouse fibroblast cells induces tumor formation upon inoculation into immunocompromised mice." (PMID 29911072, 2018). "To investigate the effect of GLDC inhibition in tumor metabolism, we performed [1-13C]pyruvate MRS to compare the pyruvate metabolism among the treatment groups." (PMID 29911072, 2018). "In summary, we demonstrate the application of hyperpolarized 13C MRS in probing changes in tumor metabolism upon GLDC inhibition." (PMID 29911072, 2018). "Since GLDC is involved in nucleotide production, it is unsurprising that tumor cells promote this gene for their growth advantage." (PMID 29911072, 2018). "And glycine dehydrogenase (GLDC), which cleavages glycine and mediates folate cycle charging, are highly expressed on tumor promoting cells and its enhanced activity is associated with tumorigenesis." (PMID 27440433, 2016). "As expected, GLDC overexpression sharply inhibited tumor volume and diminished tumor weight." (PMID 41550650, 2025). "Finally, we observed in the renal tissues of patients with poor prognosis that GLDC is highly expressed in tumors when compared with non-tumor tissues." (PMID 39781465, 2025). "We found that GLDC expression was significantly downregulated in tumor tissues." (PMID 41550650, 2025). "Additionally, in vitro and in vivo studies revealed that GLDC plays an important role in regulation of proliferation and tumor growth via interferon stimulated gene factor 3 (ISGF3)-mediated pathway." (PMID 39781465, 2025).
tumor (continued). "Moreover, depletion of GLDC in ACHN cells indeed attenuated the number of secondary tumor spheres and overexpression GLDC in A498 cells stimulated the number of secondary tumor spheres." (PMID 39781465, 2025). "Conversely, overexpression of GLDC increased cell proliferation and tumor growth." (PMID 39781465, 2025). "A recent study, however, showed a slower growth of tumor in GLDC knock-out HepG2 grafted mice." (PMID 39781465, 2025). "We further used xenograft model to detect the role of GLDC on tumor growth." (PMID 41550650, 2025). "Furthermore, GLDC protein was decreased in HCC tissues compared with para-tumor tissues and reduced GLDC was significantly correlated with poor prognosis of patients." (PMID 41550650, 2025). "However, the investigation on GLDC in tumor development is limited, and the role of GLDC is context-dependent in different cancer types." (PMID 41550650, 2025). "In NSCLC, glycine decarboxylase is essential for tumour-initiating cells." (PMID 36851259, 2023). "We believe that the increased nucleotide metabolism in PR cancer cells might be sustained by an increased influx of glycine and serine from the tumor stroma, leading to the increased activity of GLDC." (PMID 37923835, 2023). "It was suggested that GLDC may be one of the key factors regulating glycolysis in malignant tumor cells." (PMID 37781511, 2023). "We injected B-NDG mice with ARP1 cells expressing GLDC shRNA1 or scrambled shRNA subcutaneously and induced shRNA expression by adding doxycycline (2 mg/mL) to the drinking water one week after the engraftment of tumor cells." (PMID 35817773, 2022). "Correlations of GLDC and tumor immune infiltration were also identified." (PMID 36275705, 2022). "Consistent with this, lactate supplementation also increased in the A549 and H358 cell lines the proportion of the subpopulations characterized by elevated GLDC, Aldehyde dehydrogenase (ALDH) activity and SOX2 expression, critical markers associated with heightened tumor initiation capacity." (PMID 35877003, 2022). "However, GLDC was significantly decreased in ccRCC, while overexpression suppressed the proliferation and migration of tumor cells." (PMID 35873461, 2022). "However, other studies have shown that GLDC inhibits the metastasis and is positively correlated with the overall survival by acting as a tumor suppressor in HCC." (PMID 36275705, 2022). "Although we have demonstrated that GLDC mitigated by miR-30e regulates cell proliferation and tumor immune infiltration in TNBC, the regulatory mechanisms remain unknown and will be determined in future studies." (PMID 36275705, 2022). "Moreover, p62 expression was markedly decreased in the primary tumor of mice injected with GLDC-overexpressing cells compared with those transplanted with the corresponding control cells." (PMID 30804330, 2019). "Recently, GLDC has been suggested to be a putative tumor-suppressor gene in gastric cancer." (PMID 30804330, 2019). "In light of the studies show that GLDC expression is also tumor-type specific, the effect of GLDC on cellular autophagy might be tumor-type specific." (PMID 30804330, 2019). "Stronger GLDC immunostaining was observed in para-tumor tissues compared with tumor tissues." (PMID 30804330, 2019). "Here, we utilized this technique to study the changes in tumor metabolism upon GLDC inhibition." (PMID 29911072, 2018). "Whilst other reports question the role of glycine decarboxylase in cancer proliferation, the same studies note that, in some tumours, glycine levels are depleted via the conversion of glycine to serine as an alternative pathway in which serine increases allow for proliferation." (PMID 30559931, 2018). "Similarly, western blot of the tumor tissues showed that GLDC protein expression was reduced in the GLDC group as compared with the Veh and Scr groups." (PMID 29911072, 2018). "However, although both LDHB and GLDC expression levels varied significantly between tumor regions." (PMID 35877003, 2022).